TNF (tumor necrosis factor)
Diseases named in the same sentence as TNF in open-access papers (continued):
Sharing a sentence is not in itself a finding about the gene and the disease.
tumor (continued). "In the presence of TNF, NLRX1 knockdown resulted in significantly increased tumor volume, whereas overexpression attenuated tumor growth." (PMID 27105514, 2016). "Treatment of ascophyllan led to substantial increases in the proportions of IFN-γ- and TNF-α-producing CD4 and CD8 T cells in the spleen and tumor drLN, whereas IL-4- or IL-17-producing CD4 and CD8 T cells were not increased by ascophyllan treatment." (PMID 27008707, 2016). "Moreover, this study found that PADI4 may contribute to cancer development and progression by increasing the expression of CXCR2, KRT14 and TNF-α, which activate pro-inflammatory processes, angiogenesis, cell migration, cell proliferation and cell differentiation in tumor tissues." (PMID 27556695, 2016). "Inflammatory cell infiltration, fibrous tissue hyperplasia, and tumor-like epithelial proliferation were significantly reduced in the MMUS group, as were the mRNA and protein expressions of TNF-α and IL-1β." (PMID 26797392, 2016). "The expression of the molecules, including TNF‐α, IL‐1β, HIF‐1α, NF‐κB, VEGF, and MMP9 in tumor tissues was analyzed by the methods of immunohistochemistry and western blot." (PMID 27734611, 2016). "While spleen cells of both control mice and vaccinated mice produced increased levels of IL-4 in the presence of the tumor-conditioned medium, the amount produced was less than that seen for IFN-γ or the inflammatory mediators IL-6 and TNF-α." (PMID 27598146, 2016). "This included TNF-α production, the synthesis of iNOS and MPO, and also the emergence of H2O2 within the tumor." (PMID 27806313, 2016). "Tumour culture supernatant (TCS) increased the secretion of IL-10, one of the M2 phenotype markers, and decreased the secretion of IL-12 and TNF-α, M1 phenotype markers, in the HMDMs." (PMID 27404320, 2016). "Compared to the U27 tumor model group, the CTX group demonstrates significantly reduced TGF-β1 and TNF-α protein expression levels (P <0.05)." (PMID 27881109, 2016). "Immunofluorescence staining showed that TNFα increased both CD8+ cytotoxic and CD4+ helper T lymphocytes inside the tumor while IFNγ increased CD4+ T cell." (PMID 27342639, 2016). "In addition, TNF may also serve as a marker of tumor-specific T cells." (PMID 27148488, 2016). "In summary, our study provide a new slow-release recombinant TNF α-derived peptide, RMP16, which exhibits potent effects in inhibiting tumor growth and angiogenesis with less side effects via selective activation of TNFRI receptor." (PMID 26337231, 2015). "Cytokines, such as TNF-α, IL-1α, IL-1β, IL-6, and TGF-β, are produced by tumor cells and tumor-infiltrating lymphocytes and can greatly influence cellular radiosensitivity and the onset of tissue complications." (PMID 26569225, 2015). "We know that tumor-infiltrating immune cells (e.g., γδ IL-17-producing T cells, CD8+ T lymphocytes, or type I macrophages) can kill tumor cells, and that high TNFα doses can inhibit tumor growth." (PMID 26075183, 2015). "Repeated DEN-induced murine tumors share similar pathogenesis, where pro-inflammatory cytokines, such as interleukin-6 (IL-6) and tumor necrosis factor-α (TNF-α), promote tumor development." (PMID 26293671, 2015). "The levels of tumour-derived soluble factors, including GM-CSF, TNF-α, G-CSF and MCP-1, are higher than those in the tumour site." (PMID 26581194, 2015). "TNF was most potent in myofibroblast cultures, suggesting ADT induces CCL2 via paracrine interactions within the tumor microenvironment." (PMID 26327448, 2015). "As we all know, CD4+Th cells are essential to the immune response of anti-tumor and Th1 cells, a predominant Th cell subtype characterized by IFN-γ and TNF-α secretion." (PMID 26378021, 2015). "Supernatants from IL-2 + anti-CD16mAb + sAJ2-treated NK cells in combination with both anti-TNF-α and anti-IFN-γ when added to OSCSCs restored tumor cell growth to the levels which were obtained with untreated OSCSCs." (PMID 26697005, 2015).
tumor (continued). "With Dengue triggering a stronger immune response through TNFα, P and E-Selectins are also upregulated, increasing attachment rates for CTL, to allow them to infiltrate the tumor areas." (PMID 25592450, 2015). "High plasma levels of TNF-α and TNF-Rs correlated with tumor stage and a reduced mean survival time." (PMID 25624918, 2015). "The activation of macrophages facilitates the production of many immunomodulatory substances including cytokines, such as TNF-α, IL-6 and IFN-γ, which are known to play an important role in suppressing tumor cells." (PMID 26032186, 2015). "It has been reported that HIF-1 and p65 transcriptionally activate TWIST1 expression to mediate hypoxia-induced and tumor necrosis factor alpha (TNF-α)-induced EMT and tumor metastasis, respectively." (PMID 25848863, 2015). "Our model predictions of adenovirus concentration, tumor size, concentrations of CD8 + T effectors in blood and tumor, gene expression of IFNG and TNF α matched the experimental data." (PMID 26048402, 2015). "The chemotactic factors VEGF, TNF-α, and TGF-β induce podosome formation in endothelial cells along the invasive tumor front." (PMID 25734659, 2015). "In this study, we investigated the effect of SCL on the production of cytokines, including TNF-α, IFN-γ, IL-2 and IL-6, in H22 tumor-bearing mice." (PMID 26426041, 2015). "Many, including us, have compared RASSF1A and RASSF6 in their properties as a tumor suppressor, their ability to interact with MDM2, their involvement in TNF-α signaling and inflammation, as well as comparing them with Nore1- in the Ras-induced apoptosis." (PMID 26690221, 2015). "Knockdown of IFRD1 results in an increased production of pro-inflammatory cytokines and chemokines by tumour cells when stimulated with IFN-γ and TNF-α." (PMID 26055519, 2015). "Constant activation of NF-κB in cancer cells is linked to high production of inflammatory mediators such as tumor necrosis factor (TNF), interleukin-1 (IL-1), IL-6, prostaglandin E2 (PGE2), and reactive oxygen species (ROS) within the tumor microenvironment." (PMID 25918934, 2015). "TNF-α (and IL-1β) induced the release of CCL2, CXCL8 and CCL5 by MSCs and CAFs generated by prolonged stimulation of MSCs with Tumor CM of MDA-MB-231 and MCF-7 cells." (PMID 25928089, 2015). "TNFα was also shown to promote angiogenesis and induce the expression of VEGF and HIF-1α in tumor cells." (PMID 26648665, 2015). "When type 2 cells are introduced into mice, their production of TNF-α, IL-1α, or CCL5 is expected to induce the production of cytokines such as IL-6 and IL-8 in the associated fibroblast-like cells, which might in turn function as paracrine factors in tumor formation." (PMID 25673149, 2015). "By analyzing a tissue array composed of 15 non-tumor tissues and 60 NPC tissues with the detailed clinical records (Pantomics), we found a positive correlation of levels between EBERs and TNFα (P < 0.0001, r = 0.647)." (PMID 26172457, 2015). "Tumour analysis revealed increased platinum content in tumours, TNF-α induced blood vessel damage and increased tumour necrosis after combination of TNF-α and electrochemotherapy, indicating an anti-vascular action of TNF-α." (PMID 25810699, 2015). "However, the TNF response signature contains several cytokine genes that are strongly expressed by immune cells and thus the extent of inflammation and immune cell infiltration contributes to the overall activity of this signature in whole-tumour tissue samples." (PMID 26530832, 2015). "It has been shown that tumor necrosis factor-α induces MMP expression through MAPK signaling system-mediated nuclear factor-κB activation, and PAR-2 promotes numerous types of tumor cell proliferation through the MAPK signaling pathways." (PMID 25452809, 2015). "Among the tumor-infiltrating CD8+ T cells, TIM-3+ cells produced more IFN-γ, TNF-α and IL-2 compared to that by TIM-3- cells when tested by intracellular staining on day 28- post tumor inoculation." (PMID 26493689, 2015).
tumor (continued). "Second, they produce TNF-α and IFN-γ cytokines, which subsequently mediate bystander elimination of stromal cells and vasculature within the tumor microenvironment." (PMID 26173023, 2015). "Neutrophils are recruited to the tumor microenvironment by pro-inflammatory signals, including IL-8, transforming growth factor (TGF)-β, IL-4, IL-10, IL-13, GM-CSF, and TNF-α." (PMID 25734659, 2015). "In tumours treated with combination of TNF-α and CDDP, tumour vessels were dilated, with stacked erythrocytes." (PMID 25810699, 2015). "Among inflammatory mediators, some cytokines and chemokins such as tumor necrosis factor (TNF), interleukin 1 (IL-1), interleukin 6 (IL-6), interleukin 8 (IL-8) are cytokines that play role in tumor genesis." (PMID 25948470, 2015). "In the second part of the study, the effect of combined TNF-α and electrochemotherapy with different CDDP doses (1–8 mg/kg) on tumour growth was evaluated." (PMID 25810699, 2015). "In the tumor milieu, IL-1 induces expression of various metastatic mediators such as MMP, VEGF, IL-8, IL-6, TNFα, and TGFβ (reviewed in 9,13,30,31)." (PMID 26460957, 2015). "NK cells treated with IL-2 + anti-CD16mAb + sAJ2 in combination with both anti-TNF-α and anti-IFN-γ when added to MP2 cells restored tumor cell growth to the levels obtained with untreated MP2 cells." (PMID 26697005, 2015). "TRAIL is a member of the tumor necrosis factor (TNF) family, and plays an important role in cell proliferation and the induction of tumor cell apoptosis." (PMID 25729329, 2015). "Since cytokines play a key role in controlling immune responses and inflammatory reactions, we employed the ELISA assay to investigate the effects of SCL on the production of serum cytokines, including TNF-α, IFN-γ, IL-2 and IL-6, in H22 tumor-bearing mice." (PMID 26426041, 2015). "Induced by IFN-γ, IL-6, and so forth, M1 macrophages display proinflammatory, antigen-presenting, and antitumor effects, through release of soluble enzyme, TNF, and IFN and activation of T cell immune responses to inhibit tumor cells." (PMID 26161392, 2015). "It was anticipated that this new approach would eliminate the immune tolerance and tumor cell metastasis induced by IFN-γ and TNF-α." (PMID 26305550, 2015). "Our results highlighted that the anti-tumor function of Sal-YB1 therapy was mediated via TLR signalling pathway and the activation of IRAK and IκBα are determinant for TNFα release." (PMID 26286454, 2015). "Our study provided a novel mechanism whereby tumors produce a high level of tumor-promoting, proinflammatory mediators, such as MCP-1, in response to TNFα released by macrophages, in tumor microenvironments." (PMID 26167165, 2015). "In contrast, the concentration of effector CD8 + T cells in the tumor, IFNG and TNF α were increased by 100 to 1000 times compared to the prediction obtained using the c4 from model calibration." (PMID 26048402, 2015). "By contrast, the apoptosis ratio rose to 2.48 ± 0.36% for the tumor cells in medium containing TNF-α, which is significantly higher than that at TNF-α-free medium (Two sample t-test, P < 0.01), implying that TNF-α can decrease the viability of the tumor cells." (PMID 26631692, 2015). "Overall, the levels of the inflammatory markers evaluated (NAG, TNF-α, CCL2) in the implant-bearing tumors were also influenced by the inflammation phase in which the tumor cells were grown." (PMID 26158775, 2015). "Other anti-tumor genes including OSM, TNF-α and CD40LG were regulated by miRNAs of both downregulated and upregulated." (PMID 25826780, 2015). "The tumor secretes chemokines CXCL8, CCL2, IL-1, and TNF-α that recruits macrophages and suppressive CD4+CD25+CD127lowFOXP3+ Tregs to the tumor site." (PMID 25972872, 2015). "Chronic expression of the inflammatory cytokine tumor necrosis factor-alpha (TNFα), a potent NF-κB activator, can drive cancer metastasis by inducing epithelial-to-mesenchymal transition (EMT) and tumor cell migration." (PMID 26148352, 2015).
tumor (continued). "The aim of the present review is to address the role of ghrelin, myostatin, leptin, HIF, IL-6, TNF-α, and ANGPTL-4 in the regulation of energy balance, tumour development, and tumoural cell invasion." (PMID 26508818, 2015). "This was also evident with the tumour-secreted proteins at their chosen concentrations (CC: 146 ± 42.3 %, CL: 153 ± 33.4 %, IGFBP-7: 143 ± 28.5 %, VEGF-A: 146 ± 41.0 % and TNF-α: 122 ± 11.2 %)." (PMID 26407999, 2015). "Through the release of pro-inflammatory cytokines such as interleukin-1 and tumor necrosis factor alpha (TNF-α), they inhibit tumor progression." (PMID 26075202, 2015). "The rare localization of the tumor on a non-sun-exposed area and the well-established correlation of SCCs to immunosuppression could possibly imply a link of the malignancy to the lengthy use of anti-TNF-α and methotrexate for her underlying RA." (PMID 25815013, 2015). "The 9 patients with a skin GvHD stage II and III, developed significant increases of IL-6 (P = 0.0010), sIL-2R (P = 0.0049) and TNF-α (P = 0.0020) in the serum, whereas IL-8, IL-10 and IL-1ß did not significantly change." (PMID 26315105, 2015). "To better understand the relationship between tumour microenvironment parameters and cell invasion, we studied the effects of HGF, EGF, IGF, netrin, PDGF-B, TNF-α, bFGF, IL-6, NGF, TGF-β and PlGF-1 in the 3D environment." (PMID 26486848, 2015). "Additionally, the reported secretion of cytokines like TGF-β (transforming growth factor β), GM-CSF (granulocyte/macrophage-colony stimulating factor) or TNF-α (tumor necrosis factor α) by MSCs after exposure to ionizing radiation may even have a protective effect on the irradiated tumor cells." (PMID 25504442, 2015). "Transplantation of LLC cells into the flank of TNF−/− mice resulted in reduced MCP-1 serum levels, indicating that TNF plays a critical role also in vivo in inducing MCP-1 production by tumor cells." (PMID 26167165, 2015). "Gene expression of the pro-inflammatory cytokines TNF-α and CCL2 in the tumor were increased in CC compared to WSC, p = 0.020 and p = 0.0354, respectively." (PMID 26732354, 2015). "Cytokines such as IL-6 can promote an EMT and endow tumor cells with cancer stem cell properties, and TGFβ, which has well-established roles in the induction of EMT, can cooperate with TNF to induce EMT, stemness and tumorigenicity." (PMID 26207831, 2015). "Hemocytes (blood cells) are recruited to the tumor and secrete TNF, thereby activating JNK signaling within the tumor cells." (PMID 26207831, 2015). "The protocol described in this study was feasible in expanding tumor infiltrating lymphocytes from patients with primary HCC disease, and these expanded T cells have displayed high levels of IFN-γ and TNF–α expression." (PMID 26515587, 2015). "Accordingly, inhibition of COX-2 prior or during PDT with NSAIDs decreased tumor cell survival in a variety of (tumor) cell lines, which coincided with a reduction in levels of PGE2 and the proangiogenic factors MMP9, TNF-α, IL-1β, IL-10, and VEGF." (PMID 26516076, 2015). "Non-tumor MCF10A cells were treated with Y-27632 (Y27), H1152, blebbistatin (Blebb), and/or low doses of nocodazole (Noc) prior to TNFα stimulation." (PMID 26148352, 2015). "The expression of TNFα was found in both 4T1 and LLC tumors; thus, TNFα is available in both tumors and capable of stimulating tumor cells to produce high levels of MCP-1." (PMID 26167165, 2015). "A number of studies have reported that TNF-α can induce the expression of MMPs, interleukin (IL)-8, CXC chemokine receptor type 4 (CXCR), VEGF and MCP-1, thus enhancing tumor cell invasion and metastasis." (PMID 24676340, 2014). "First pre-clinical studies of the combination of these antibodies to achieve blockade of both CTLA-4 and PD-1 showed increased tumor infiltration by CD4+ and CD8+ T-cells, enhanced IFNγ and TNFα production, and reduced amounts of Tregs." (PMID 24822170, 2014).
tumor (continued). "The interaction of tumor necrosis factor-α (TNF-α) with its receptors: TNFRSF1A and TNFRSF1B is critical for the promotion of tumor growth, invasion and metastasis." (PMID 25010932, 2014). "We demonstrated that activation of fibroblasts with TNF, a cytokine with a central role in the pathogenesis CD, is sufficient to reduce their ability to induce STAT1 signaling in tumor cells." (PMID 24818101, 2014). "Experimental data support a tumor-promoting role for B cells for skin sarcoma development, showing immunoglobulin deposition within the TUMIC that was dependent on TNFα." (PMID 25072019, 2014). "Numerous studies have shown that TAMs play a critical role in modulating angiogenesis in the tumor environment and are able to secrete many proangiogenic factors such as VEGF, TNF-α, IL-8, and bFGF." (PMID 24721786, 2014). "In vivo, tumour growth, proliferation, vessel density, and effects on vascular endothelial growth factor (VEGF) and tumour necrosis factor alpha (TNF-alpha) expression were examined following treatment with pK1-5." (PMID 24895598, 2014). "Natural killer (NK) cells eliminate virus-infected and tumor cells through the release of perforins and granzymes; they also produce Interferon gamma (IFN-γ) and Tumor necrosis factor alpha (TNF-α), which induce apoptosis in target cells." (PMID 25302050, 2014). "In a tumour milieu LCN2 is potentiated by proinflammatory cytokines Il-1β, TNF-α, and IL-17 and is involved in the epithelial to mesenchymal transition (EMT)." (PMID 25010215, 2014). "Whilst there is clear evidence that IL-10 is immunosuppressive and protumorigenic, there is also new contradictory evidence that IL-10 can enhance apoptosis and downregulate VEGF, TNF-α, and IL6 production by TAMs to suppress angiogenesis and tumor growth." (PMID 24955376, 2014). "Although TNF-α has antitumor activity, there is growing evidence that suggests that endogenous TNF-α acts as a tumor promoter." (PMID 25548907, 2014). "In tumor masses, the immunoreactivities of caspase-3 and PARP- apoptotic marks, COX-2, iNOS and TNF-α were additionally observed by immunohistochemistry." (PMID 25477992, 2014). "They directly mediate the death of tumor cells, and also produce inhibiting factors such as IFN-γ, TNF-α and IL-2." (PMID 25594054, 2014). "Mice immunized with ablated tumor cells/supernatant released significantly higher levels of IFN-γ and TNF-α compared with ablated tumor cells alone, ablated supernatant alone, or mock media controls." (PMID 25153727, 2014). "All these cytokines, in different combinations, caused recruitment (IL-8 and GM-CSF) and survival, activation, and proliferation (TNF-α, IL-8, and IL-17) of MDSC that in turn mediate immunosuppression and promote tumor growth." (PMID 25505472, 2014). "After matching the TNF-α-mediated mouse genes to their human orthologs, we compared the expression patterns of the TNF-α-mediated genes in normal and tumor lung tissues obtained from humans." (PMID 25548907, 2014). "Tumor necrosis factor-α (TNF-α) exhibits potent antitumor activity, alters endothelial barrier function, reduces tumor interstitial pressure, and mediates immune responses." (PMID 24466321, 2014). "While we found a correlation between heightened TNF-alpha levels and increased VEGF expression in vitro, VEGF was decreased in tumour and liver tissue." (PMID 24895598, 2014). "Overall, the results of this study showed that the administration of asiaticoside significantly reduced the percent of tumour growth that is significantly correlated with MIBI uptake ratios, and this is also correlated with caspase-3, TNF-α and IL-1β values." (PMID 24667059, 2014). "Inhibition of TNF-α-induced apoptosis was identified as the mechanism of BCG action as assessed in A549 and several other tumor cells." (PMID 25208737, 2014). "The expressed IL-21 not only regulated the levels of IFN-γ and TNF-α in the mouse serum but also increased the expression of NKG2D and MIC A molecules in the tumor tissues." (PMID 24444073, 2014).